LIN28B (lin-28 RNA binding posttranscriptional regulator B)
Diseases named in the same sentence as LIN28B in open-access papers (continued):
Sharing a sentence is not in itself a finding about the gene and the disease.
cancer (160 papers, 2010 to 2026). A tumor composed of atypical neoplastic, often pleomorphic cells that invade other tissues. "Similar to that of LIN28B, let-7 dysregulation is associated with poor prognosis and increased metastatic potential in several cancer types, including breast, lung, colorectal, and ovarian cancers." (PMID 37318881, 2023). "Expression of protein lin‐28 homolog B (LIN28B), a regulator of developmental timing, is upregulated in several cancers, including G3 MB, and is associated with worse survival in this disease." (PMID 37341142, 2023). "The studies collectively indicate that LIN28B overexpression is strongly linked to cancer stem-ness, tumor progression, metastasis formation, and poor prognosis in OSCC patients, indicating the clinical relevance of LIN28B in this tumor entity." (PMID 37304235, 2023). "Genes that have been shown to play a role in this dysregulation include PIWIL1, LIN28A and LIN28B, and have been associated with poorer patient outcomes and more aggressive cancer subtypes." (PMID 36980876, 2023). "We and others have shown that LIN28B expression is associated with metastatic behavior of cancer cells in murine xenograft models." (PMID 37318881, 2023). "LIN28A and LIN28B are upregulated in approximately 15% of human tumors and cancer cell lines, with activation associated with poor prognosis and advanced malignancy." (PMID 36307883, 2022). "The loss of IGF2BP1 inhibits Cdc34, Lin-28B, and K-Ras, suppresses cancer cell proliferation and anchorage-independent growth, and promotes caspase-mediated cell death." (PMID 34203267, 2021). "The negative regulators of let-7a biogenesis including Lin28a, Lin28b and hnRNP A1 are associated with cancer formation." (PMID 33669264, 2021). "LIN28B in the peripheral blood mononuclear cells is shown to be an oncofetal circulating cancer stem cell-like marker associated with recurrence of HCC." (PMID 32571380, 2020). "Apart from the current study, Park and colleagues illustrated that Lin28B/let-7 interaction played a pivotal role in cancer stem cell-associated X-ray resistance." (PMID 32219065, 2020). "The relationship of LIN28B polymorphisms to cancer development, progression and metastasis, and patient prognosis, has also been investigated in some cancers." (PMID 32571380, 2020). "Overexpression of Lin28b has been observed in human cancers and Lin28B upregulation is associated with poor prognosis and tumor recurrence." (PMID 29970131, 2018). "In the present study, we observed that simvastatin suppressed LIN28B, which is a key player in tumorigenesis, and subsequently restored the let7-miRNA family as a novel mechanisms underlying the anti-cancer effects of simvastatin in human CRPC cells." (PMID 28910332, 2017). "Overexpression of LIN28B has been associated with advance human malignancies and cancer stem cells (CSCs), including AML." (PMID 28693523, 2017). "Reactivation of either LIN28A or LIN28B is a hallmark of many human cancers where the expression of these proto-oncogenes is typically mutually exclusive." (PMID 28400788, 2017). "through targeting specific genes such as MTA1 (metastasis-associated gene 1), Lin28B (Lin-28 homolog B) and Gab2 (Grb2-associated binding protein 2) in various cancers." (PMID 28881624, 2017). "Lin28 and Lin28B are implicated in tumorigenesis in different cancers, but Lin28B is more frequently overexpressed in human cancers." (PMID 28947981, 2017). "Gain-and loss-of-function studies have further revealed that LIN28B/LIN28 promotes cancer cell proliferation, invasion and metastasis both in vitro and in vivo largely through let-7 repression." (PMID 26478718, 2015). "Noticeably, comprehensive analyses of LIN28 and LIN28B expression in human cancers pointed to LIN28B as the more relevant homologue underlying tumorigenesis." (PMID 26478718, 2015). "High levels of LIN28A/LIN28B proteins are associated with many cancer biological behaviors and poor prognosis." (PMID 26123544, 2015).
cancer (continued). "In this study we found that the oncofetal cancer-stem-cell-like marker, Lin28B in peripheral blood mononuclear cells is associated with early recurrence of HCC." (PMID 24244607, 2013). "The observed upregulation of the stem cell gene LIN28B in ESFT is consistent with its reported function as an oncogene whose expression in human cancer is associated with unfavorable prognosis." (PMID 21853155, 2011). "LIN28 and LIN28B overexpression is found in approximately 15% of human cancers and is associated with poor outcomes." (PMID 24213119, 2011). "The LIN28B/let-7 axis regulates cell differentiation and is associated with various cancers." (PMID 38976670, 2024). "Moreover, the LIN28B/let-7 axis has been implicated in cancer cell stem-like property acquisition and regulation of key cancer stemness transcription factors." (PMID 37991019, 2023). "Here we show that Lin28b/let-7 pathway is indispensable for modulating the expression of Wnt5a in tumor epithelium, which could be secreted and then up-regulates Lin28b in cancer-associated fibroblasts (CAFs)." (PMID 37898598, 2023). "Increased levels of LIN28B have pathological associations with many cancers, including colon cancer, lung cancer, hepatocellular carcinoma, ovarian cancer, germ cell tumors, prostate cancer, leukemia, breast cancer, oral squamous cell carcinoma, glioma and melanoma." (PMID 36766779, 2023). "The lin28B/Let-7c/MYC axis is associated with the occurrence of many cancers." (PMID 36057607, 2022). "Lin28A and Lin28B are aberrantly expressed in a plethora of tissue malignancies, and activation of either Lin28A or Lin28B is responsible for the global post-transcriptional downregulation of let-7 miRNAs in many cancers, which is associated with advanced tumor stages and poor patient outcomes." (PMID 34572067, 2021). "Moreover, we observed that FAM83F overexpression induced the reactivation of stem cell markers such as Sox2, Nanog and Lin28b usually associated cancer stem cells and undifferentiated thyroid cancer." (PMID 30881348, 2019). "Furthermore, miR-203 caused a significant restraint of the expression of CD133 and LIN28B, two genes associated with cancer cells stemness, both in HepG2 and Huh7 cells." (PMID 31073374, 2019). "Furthermore, high levels of LIN28B proteins are associated with the biological behaviors and poor prognosis of many cancers." (PMID 28218277, 2017). "Interestingly, overexpression of mammalian LIN28A and LIN28B is often associated with malignant tumors in human." (PMID 27296804, 2016). "The hypothesis tested was that circulating Lin28B detected in peripheral blood mononuclear cells is an oncofetal cancer-stem-cell-like marker associated with recurrence or worse survival in HCC." (PMID 24244607, 2013). "Recent studies have also documented that lin28B could block the accumulation of mature let-7, which in turn regulates “stemness” by inhibiting self-renewal, the cellular characteristics of cancer stem-like cells associated with tumor recurrence." (PMID 20805998, 2010). "Thus, LIN28B is associated with poor prognosis and tumor metastasis in diverse cancers." (PMID 37318881, 2023). "Indeed, LIN28B expression in adult tissues is associated with 20 different human cancers." (PMID 34793513, 2021). "To explore the functions of Lin28B in cancer cells, we first established two stably transfected clones of H1299 cells, in which Lin28B was knocked down by co-transduction of the cells with lentivirus encoding each of the shRNA specific for Lin28B, designated sh-Lin28B-1 and sh-Lin28–2." (PMID 29301498, 2018). "Collectively, our findings highlight dual targeting of PARP and LIN28B as a promising MA management approach in patients with advanced cancers, with the potential to improve patient quality of life." (PMID 41572432, 2026). "While both LIN28A and LIN28B paralogs are critical to various human developmental processes, LIN28B has emerged as a potent oncogene across several cancers." (PMID 39808497, 2025).
cancer (continued). "Efforts to develop LIN28B inhibitors are ongoing, highlighting its translational relevance across multiple cancer types." (PMID 40265419, 2025). "It is also important to note that the precise mechanisms by which LIN28B regulates lipid accumulation in normal and cancer cells are still not fully understood." (PMID 40265419, 2025). "By regulating the IGF2‐IGF1R axis, LIN28B triggers angiogenesis and facilitates the spread of cancer cells." (PMID 40679030, 2025). "Among these, the role of LIN28B has garnered attention as an RNA-binding protein influencing gene regulation and cancer progression." (PMID 39808497, 2025). "circHIPK3 contains multiple sites for the same RBPs (e.g., DDX54, EIF4A3, FMR1, IGF2BP1, IGF2BP2, LIN28B and MOV10), many of which are involved in chemoresistance and organelle-like structures, such as Cajal body and P-body which are associated with cancer." (PMID 40061896, 2025). "Consistently with a broad role in cancer, LIN28B is found highly expressed in a wide spectrum of cancer cell lines, including myeloid, liver, and central nervous system cells, compared to other tissues." (PMID 38704454, 2024). "Overall, our data reveal a mechanism by which SOX6 can act as a tumor suppressor in LIN28B-positive cancer cells." (PMID 38704454, 2024). "The metabolic phenotype of cancer cells carrying the LIN28B oncogene has been the subject of intense investigation over the years, since the induced metabolic changes provide the energy and biomacromolecules necessary for tumor cell growth." (PMID 38338881, 2024). "LIN28B also plays a role in pluripotency, but its involvement in cancer has been more extensively investigated." (PMID 39456596, 2024). "Increased aerobic glycolysis in cancer stem cells expressing LIN28B can also be regulated via the LIN28B/MYC/miRNA-34a-5p axis." (PMID 38338881, 2024). "They discovered that a LIN28B/let-7 regulatory loop regulates ALDH1+ cancer stem cells and that LIN28B maintains the population of ALDH1+ tumor cells by controlling let-7." (PMID 38612395, 2024). "Reactivation of either LIN28A or LIN28B is common in many human cancers, where their expression is usually mutually exclusive." (PMID 38732012, 2024). "LIN28B suppresses the biogenesis of the let-7 family microRNA and reduced let-7 expression has been observed in numerous human cancers." (PMID 39456596, 2024). "This work demonstrates that LIP is both a regulator of the let-7/LIN28B regulatory circuit and an inducer of cancer type metabolic reprogramming." (PMID 38612395, 2024). "Other molecules such as LI71 bind the cold shock domain and have efficacy against LIN28B + cancer cell lines." (PMID 38601080, 2024). "Our results reveal that ADAMTS9-AS2 promotes neuronal differentiation and inhibits cancer stemness by directly binding to LIN28B and modulating MYCN activity." (PMID 37991019, 2023). "LIN28B expression significantly promotes tumor growth, tumor progression, cancer cell stemness, cancer aggressiveness and metastasis formation." (PMID 37304235, 2023). "Several more publications provide further insight regarding LIN28B’s stimulating effect on cancer progression, metastasis formation, and therapy resistance in the colon cancer entity." (PMID 37304235, 2023). "Deletions in or near prominent cancer-associated genes (for example, ALK, LIN28B, PDGFD and WNT7B) were also detected." (PMID 37188965, 2023). "In summary, these findings provide novel and interesting capabilities of LIN28B regulating the micromilieu of pre-metastatic niches, therapy resistance, cancer cell reprogramming and consequences on tumor progression." (PMID 37304235, 2023).
cancer (continued). "The majority of the publications presented here indicate the potential relevance of LIN28B in research as a biomarker for cancer invasion and aggressiveness and in the clinic as a therapeutic target and diagnostic tool." (PMID 37304235, 2023). "LIN28B has also been suggested to play a role in pluripotency; however, its role in cancer has been more extensively investigated due to increasing evidence demonstrating that LIN28B serves as an oncogene." (PMID 37318881, 2023). "The roles of Lin28A and Lin28B in cancer development and progression have been elucidated over the last decade." (PMID 36230562, 2022). "Taken together, these results support the model in which enhanced TGF-β signalling by LIN28B promotes cancer stem cell-like potential in CCA." (PMID 34548635, 2022). "For example, a LIN28B variant, LIN28B-TST, was found to be specifically expressed in tumor samples and critical for cancer cell proliferation and tumorigenesis." (PMID 36357395, 2022). "The abnormal re-activation of LIN28B is commonly seen in diverse human malignancies and serves as an oncoprotein by modulating tumor progression, metastasis and cancer immunity." (PMID 35780125, 2022). "We showed that Lin28B gene disruption inhibited cancer cell stemness and suppressed NEPC tumor progression." (PMID 36428779, 2022). "We have shown that Lin28B drives cancer stemness phenotypes and promotes cancer cell lineage switch to a neuroendocrine lineage." (PMID 36428779, 2022). "In fact, previous reports have shown that LIN28B is evidently overexpressed and plays a tumor-promoter role in multiple human cancers." (PMID 35945579, 2022). "Here, we show that enhanced LIN28B expression promoted cancer stem cell-like properties in CCA, including enhanced cell migration, epithelial-to-mesenchymal transition (EMT), increased cell proliferation and spheroid formation." (PMID 34548635, 2022). "Mechanistically, akin to IGF2BP1, IGF2BP3 protects let-7 target transcripts, including HMGA2 and LIN28B, by disrupting RISC association and upregulating expression in development and cancer." (PMID 36307883, 2022). "In this study, ZKD of Lin28B bound the RPS29 protein, which was shown to correlate with low patent survival, cause cell cycle arrest, and induce cancer cell morphological differentiation." (PMID 36230562, 2022). "LIN28B is a known oncoprotein aberrantly expressed in a subset of human cancers, including ESCC, which is consistent with our results." (PMID 34345012, 2021). "A series of in vitro experiment suggests that ELF-1- and/ or STAT1-dependent Lin28b regulation is responsible for Let-7 induction in Fhit-expressing cancer cells." (PMID 33437205, 2021). "As a direct target of HOXB7 emerging cancer gene and pluripotency factor LIN28B was identified that sustained the expansion of a subpopulation of cells with stem cell characteristics." (PMID 32830458, 2021). "LIN28B is functionally driving malignant transformation and relevance to the worse disease outcomes by promoting cancer aggressiveness." (PMID 34837926, 2021). "LIN28A and LIN28B, which negatively regulate members of the let-7 miRNA family, promote cell proliferation in cancers derived from various origins." (PMID 32967226, 2020). "LIN28A and LIN28B regulate proliferation by directly or indirectly binding to and affecting the expression levels of cancer growth-related genes, including HER2 and HMGA1, in both let-7-dependent and -independent manners in breast cancer." (PMID 32967226, 2020). "Loss of Rpl22 in mice activates the stress-induced NF-κB pathway, increasing expression of the stemness factor Lin28B, which then leads to cancer." (PMID 32432546, 2020). "LIN28B is responsible for the post-transcriptional downregulation of the let-7 in many types of cancers." (PMID 31907362, 2020).
cancer (continued). "Pri-miR-26a-1 is a novel, small RNA that involves several signaling pathways and acts as a tumor suppressor in tumorgenesis and cancer development by binding to Lin28B and Zcchc11 to suppress cancer development and metastasis." (PMID 33052138, 2020). "In gastric cancer, LIN28B promotes cancer cell stemness by stabilizing neuropilin 1 mRNA and activating the downstream Wnt/β-catenin signaling." (PMID 32528950, 2020). "Regarding pseudogenes, the downregulation of transcribed pseudogene RPSAP52 enhances the oncofetal HMGA2-IGF2BP2-RAS axis through impairing the balance between the oncogene LIN28B and tumor suppressor let-7 in human cancers." (PMID 33027767, 2020). "In lung cancer cells, LIN28B stabilizes the mRNA of Delta-like protein 3 and induces cancer cell proliferation and migration." (PMID 32528950, 2020). "One prominent example in cancer is the LIN28B/IGF2BP-containing network, which antagonizes tumor-suppressive regulation by let-7 miRNAs." (PMID 32545414, 2020). "Several studies have demonstrated that LIN28B can promote proliferation, and invasion of cancer cells." (PMID 32651364, 2020). "The new evidence has shown that exosomes from cancer cells contain Lin-28 homolog B (Lin28B) which can be transmitted to adjacent cancer cells." (PMID 32756339, 2020). "LIN28B increases cancer cell invasion in intestinal and colorectal adenocarcinomas in murine models." (PMID 31440515, 2019). "Our findings suggested that Lin28A and Lin28B are promising biomarkers, and the detection of Lin28A and Lin28B expression in cancer patients is of potential value for monitoring patients’ survival." (PMID 30976203, 2019). "In line with the depicted feed-back loop of the repression of miRNA LET7 by embryonic transcription factor LIN28B in cancer stem cells, Markopoulos and coworkers recently reviewed more than 150 miRNAs acting on NF-κB in cancer." (PMID 31083587, 2019). "LIN28B knockdown in cancer cells reduces their proliferative and invasive abilities in vitro and inhibits both primary and metastatic tumor growth in vivo." (PMID 31440515, 2019). "The mammalian homologs of Lin-28, Lin28 (also called Lin28A) and Lin28B, are promising cancer biomarkers." (PMID 30976203, 2019). "As a bona fide cancer-related protein, Lin28B is subject to polyubiquitination that leads to the enhancement of let-7 biogenesis." (PMID 29301498, 2018). "Functional characterization of the downstream molecular networks regulated by LIN28B will contribute to developing novel targeted therapeutic strategies for human cancer." (PMID 30174831, 2018). "Functional experiments have shown that GLDC is essential to lung cancer stem cells: particularly, both GLDC and LIN28B are required for cancer stem cell growth and tumorigenesis; GLDC overexpression was able to promote cell proliferation and transformation." (PMID 30060526, 2018). "LIN28A and LIN28B expression in cancer is typically mutually exclusive and expression of either gene is almost invariably associated with poor prognosis." (PMID 30057901, 2018). "Increasing evidence demonstrates that LIN28B is activated in cancer and serves as a critical oncogene." (PMID 30174831, 2018). "By contrast, increasing LIN28B expression reduced PCD sensitivity, leading to the conclusion that LIN28B inhibits PCD in cancer cells." (PMID 30174831, 2018). "A high Lin28A or Lin28B and low let-7 expression pattern is found in approximately 15% of human cancers." (PMID 29301498, 2018). "Xiaomin Zhong’s team at Sun Yat-Sen University knocked down the gene, LIN28B, in cancer cell lines and discovered that this increased their response to a chemical, which induces programmed cell death (PCD)." (PMID 30174831, 2018). "Altogether, these findings unveil a previously unexplored role of PHGDH in the regulation of self-renewal and stemness factors (KLF4, Oct4, Nanog, Sox-2, and Lin28B) in cancer stem-like cells." (PMID 30250195, 2018).